GIP (gastric inhibitory polypeptide)
Diseases named in the same sentence as GIP in open-access papers (continued):
Sharing a sentence is not in itself a finding about the gene and the disease.
type 2 diabetes (continued). "Several GLP-1 and dual GIP/GLP-1 receptor agonists have been developed to harness these pharmacological effects in the treatment of type 2 diabetes, with some demonstrating robust effectiveness in weight management and prevention of cardiovascular diseases." (PMID 39114288, 2024). "Future head-to-head studies comparing the two agents or including recent potent GLP1RAs and GLP1/GIP co-agonists, to expand on the present observations, and thereby enhance tailored therapeutic approaches for managing type 2 diabetes are warranted." (PMID 38956548, 2024). "When type 2 diabetes patients are compared to healthy individuals who respond to oral glucose in a dose-dependent manner, the former group either has reduced GIP levels or has developed beta-cell resistance to GIP." (PMID 38255264, 2024). "Glucagon and GLP-1 receptor dual agonists and GLP-1, GIP, and glucagon receptor triple agonists have been developed, and we will be able to use them for the treatment of metabolic diseases including type 2 diabetes, in future." (PMID 40607157, 2024). "These safety findings are similar to those reported for therapies based on GLP-1 or GIP/GLP-1 agonism for the treatment of type 2 diabetes or obesity." (PMID 38858523, 2024). "The importance of modern GLP‐1 agonists and dual GLP‐1 GIP agonists increases since these drugs target obesity and type 2 diabetes." (PMID 37101029, 2023). "Although GIP secretion can remain near‐normal in individuals with type 2 diabetes, the insulin response to GIP is markedly impaired; in contrast, the insulin response to GLP‐1 is preserved." (PMID 37602910, 2023). "GLP-1 and GIP hormones play important roles in regulating insulin secretion and management of Type 2 diabetes by augmenting glucose-stimulated insulin secretion via the cAMP signaling pathway." (PMID 37133312, 2023). "GIP stimulates glucagon secretion in healthy individuals and those with type 2 diabetes, especially at lower plasma glucose concentrations, whereas the insulinotropic actions are more prominent during hyperglycaemia." (PMID 37430117, 2023). "In type 2 diabetes, GIP has a limited ability to stimulate insulin secretion during hyperglycaemia and does not significantly reduce plasma glucose concentrations." (PMID 37430117, 2023). "In this systematic review, we aim to explore the latest findings on the cardiovascular effects of glucagon-like peptide-1 (GLP-1) agonists and dual GLP-1/glucose-dependent insulinotropic peptide (GIP) agonists in patients with type 2 diabetes mellitus." (PMID 37859909, 2023). "Inhibitors of DPP-4 lower glucose levels in individuals with type 2 diabetes because they prevent the degradation and inactivation of the intact biologically active molecular forms of GIP and GLP-1." (PMID 37430117, 2023). "Insulin secretory responses (insulin and C-peptide rises above baseline) during the administration of exogenous human synthetic GIP were uniformly much smaller in those with type 2 diabetes than in healthy individuals." (PMID 37430117, 2023). "After the publication of the first report that porcine GIP has little insulinotropic activity in people with type 2 diabetes, the interest in GIP dramatically decreased, as shown by the number of publications on GIP after 1987." (PMID 37430117, 2023). "In patients with type 2 diabetes mellitus, decreased levels of glucagon-like peptide-1 (GLP-1) and glucose-dependent insulinotropic polypeptide (GIP) have been reported to cause hyperglycemia." (PMID 36770960, 2023). "Recently, renewed discussion on the therapeutic potential of GIP in the long-term treatment of type 2 diabetes has been triggered by clinical findings with the dual GIP/GLP-1 receptor agonist tirzepatide." (PMID 37430117, 2023). "Accordingly, the glucagonostatic effect of GLP-1 is fully preserved in those with type 2 diabetes, and GIP also stimulates glucagon secretion in those with type 2 diabetes." (PMID 37430117, 2023).
type 2 diabetes (continued). "In fact, GIP infusions have been shown to be able to stimulate NEFA esterification in the AT of patients with type 2 diabetes (T2D) despite being unable to stimulate insulin secretion, which occurs in euglycemic individuals." (PMID 37233628, 2023). "The next chapter of incretin-based therapy for lowering cardiovascular risk in type 2 diabetes will be represented, most likely, by the development of tri-agonists capable of simultaneous activation of GLP-1, GIP and glucagon receptors." (PMID 37542009, 2023). "The insulinotropic effect of GIP is diminished in patients with type-2 diabetes but is restored upon near normalization of glycemia upon 4-week administration of insulin." (PMID 35299971, 2022). "As patients with type II diabetes show significant insulin resistance to exogenous GIP, these pigs are good models to study the role of GIP in glucose homeostasis and pancreatic development." (PMID 35343091, 2022). "The serum GIP concentration increases with increases in body mass index (BMI) in humans with type 2 diabetes, and it has been shown to increase the blood flow to adipose tissue and increase lipid deposition." (PMID 35440936, 2022). "In type 2 diabetes, a 240-min GIP infusion lowered serum NEFA concentrations, promoting TG accretion in subcutaneous adipose tissue." (PMID 36010335, 2022). "In patients with type 2 diabetes (T2D), the incretin effect is impaired, partly due to a reduction in GIP efficacy." (PMID 35846282, 2022). "Tirzepatide is the first dual GIP/GLP-1 receptor co-agonist approved for the treatment of type 2 diabetes in the USA, Europe, and the UAE." (PMID 36050763, 2022). "If GIPR agonism induced by tirzepatide treatment is responsible for enhanced ß-cell secretion, it is reasonable to assume a time-dependent process re-establishing GIP as an effective insulin secretagogue even in advanced type 2 diabetes." (PMID 36050763, 2022). "In fact, in type 2 diabetes GLP-1 maintains its stimulatory activity while GIP loses it and this is still unexplained." (PMID 35405964, 2022). "The MR estimates for CRP, HDL-C and triacylglycerol levels exceeded and were statistically heterogeneous to those obtained for reduced type 2 diabetes liability more generally, suggesting additional mechanisms specific to GIP signalling." (PMID 34505161, 2021). "We selected the genetic proxies for sustained GIP signalling based on its known biological effects in healthy individuals, namely improved glycaemic control and reduced liability to type 2 diabetes." (PMID 34505161, 2021). "GIP expression is significantly greater in both the small intestine and colon of patients with Type 2 diabetes than healthy individuals." (PMID 34660576, 2021). "Incretin hormone secretion is essentially normal but the insulinotropic effect of GIP in type 2 diabetes is attenuated markedly." (PMID 33897622, 2021). "Especially the development of diverse GLP-1 receptor agonists has shown immense success, whereas studies of GIP monotherapy in patients with type 2 diabetes have consistently been disappointing." (PMID 33339298, 2020). "In comparison to conventional ELISA, receptor-mediated bioassay reflects dynamic change of GIP by DPP-4 inhibitor treatment in subjects with type 2 diabetes." (PMID 32390941, 2020). "Since numerous studies have shown that the inhibition of DPP-4 elevates GLP-1/GIP levels, this approach is widely used to treat type 2 diabetes." (PMID 33328991, 2020). "After an overnight fast, 12 patients with type 2 diabetes received infusions of GIP (4 pmol/kg/min), GLP-1 (1.2 pmol/kg/min) or the combination of both for 6 h." (PMID 31443356, 2019). "The reduced insulinotropic effect of GIP is considered an important pathophysiological component of type 2 diabetes, which, so far, has rendered the pursuit of GIP monotherapy as anti-diabetic strategy unattractive." (PMID 31443356, 2019).
type 2 diabetes (continued). "There is also the possibility that resistance to GIP observed in patients with type 2 diabetes can be overcome by lowering circulating levels of glucose." (PMID 31330984, 2019). "The insulinotropic effect of GIP is severely reduced in patients with type 2 diabetes, while the glucagonotropic effect of GIP seems to prevail." (PMID 31443356, 2019). "While the secretion of GIP in patients with type 2 diabetes appears to be normal, the insulinotropic ability of GIP is severely reduced at both physiological and pharmacological concentrations in these patients." (PMID 31443356, 2019). "This is surprising, given that the GIP component of tirzepatide is glucagonotropic in patients with type 2 diabetes as would be expected from co-infusion studies with GIP and GLP-1." (PMID 31443356, 2019). "Observations made by our group during clamping of plasma glucose at different glycemic levels, seem to indicate that the glucagonotropic action of GIP in type 2 diabetes is preserved during periods of hypoglycemia and/or euglycemia." (PMID 31443356, 2019). "Initial interest in GIP-based therapies waned following studies showing that the insulinotropic properties of GIP are attenuated in patients with type 2 diabetes." (PMID 31447324, 2019). "Increased postprandial GIP responses have been reported in patients with type 2 diabetes and recent findings implicate GIP as a “diabetogenic” hormone." (PMID 31921879, 2019). "Regarding the modulation of glucagon secretion by GIP in type 2 diabetes, some studies have found that in patients with type 2 diabetes, the glucagonotropic action of GIP prevails even during hyperglycemia." (PMID 31443356, 2019). "Contrary to dogma, these studies also demonstrated that exogenously administered GIP remained fully active in humans with mild type 2 diabetes mellitus." (PMID 29466430, 2018). "Although GIP secretion is preserved, the insulinotropic effect of GIP is diminished in type 2 diabetes." (PMID 29997575, 2018). "In previous investigations of healthy individuals and in patients with type 2 diabetes, addition of guar gum to a standard oral glucose load or test meal dampened post-prandial rise in plasma insulin and gastric inhibitory polypeptide." (PMID 30170579, 2018). "Conversely, the effects of Xen on GIP-mediated insulin and glucagon release were greatest in humans with impaired glucose tolerance but blunted in those with mild type 2 diabetes mellitus." (PMID 29466430, 2018). "As such, it seems unlikely that stand-alone GIP-based drugs would have therapeutic value for type 2 diabetes." (PMID 28004148, 2017). "Near normalisation of blood glucose levels has been shown to restore the insulin-secretory effect of GIP in both animal models of type 2 diabetes and in humans with this condition, providing evidence that defective GIP receptor signalling is reversible." (PMID 28004148, 2017). "A defect in the postprandial insulin-secretory incretin response, mediated by the gut hormones glucagon-like peptide-1 (GLP-1) and glucose-dependent insulinotropic peptide (GIP), is a specific pathophysiological characteristic of type 2 diabetes." (PMID 28004148, 2017). "Nonetheless, it is clear from the current study that novel treatment options aimed at overcoming GIP resistance in type 2 diabetes have therapeutic potential." (PMID 28004148, 2017). "Notwithstanding this, strategies to overcome defective GIP action in type 2 diabetes would be of considerable interest." (PMID 28004148, 2017). "In agreement, observations from our laboratory and others confirm the GIP-potentiating effects of xenin under normal and type 2 diabetes conditions." (PMID 28004148, 2017). "Consistent with our observations, the positive actions of GIP on islet and beta cell architecture have previously been shown to improve beta cell function and glycaemic control in animal models of type 2 diabetes." (PMID 28004148, 2017).
type 2 diabetes (continued). "As such, therapeutic interventions that combine the biological actions of xenin and GIP, and potentially restore GIP action in type 2 diabetes, would have particularly exciting potential." (PMID 28004148, 2017). "As expected, the biological action of GIP was severely perturbed in high-fat-fed mice, akin to the situation in patients with type 2 diabetes." (PMID 28004148, 2017). "This approach is very encouraging given that the issue of GIP sensitivity in type 2 diabetes is now being addressed." (PMID 28004148, 2017). "The results reveal that GIP/xenin hybrid molecules require further consideration as a treatment option for type 2 diabetes." (PMID 28004148, 2017). "The difference in AUC−15–240 min-GIP between FR and MR in type 2 diabetes reached statistical significance." (PMID 26704625, 2016). "The gut incretin hormones glucagon-like peptide-1 (GLP-1) and glucose-dependent insulinotropic peptide (GIP) have a major role in the pathophysiology of type 2 diabetes." (PMID 27623947, 2016). "Among the gut hormones, glucagon-like peptide 1 (GLP-1) and glucose-dependent insulinotropic polypetide (GIP), referred to as incretins, have gained enormous attention due to their insulinotropic action and relevance in the treatment of type 2 diabetes (T2D)." (PMID 27148273, 2016). "Elevation of AUC−15–240 min-GLP-1 and AUC−15–240 min-GIP by MR in type 2 diabetes and controls and elevation of AUC−15–240 min-GLP-1 by FR in type 2 diabetes reached statistical significance." (PMID 26704625, 2016). "Insulin and C-peptide levels were decreased by fish and meat preload in type 2 diabetes and healthy individuals, despite enhanced secretions of GIP and GLP-1 that should stimulate insulin secretion glucose-dependently." (PMID 26704625, 2016). "As such, normalisation of blood glucose levels has also been shown to restore GIP insulin secretory function in both rodents and humans with in type 2 diabetes." (PMID 27032106, 2016). "In patients with type 2 diabetes, 4 weeks of intensive insulin therapy aiming for near-normal glycaemia partially re-established the insulinotropic properties of GIP." (PMID 25613747, 2015). "Glucagon-like peptide-1 (GLP-1) and glucose-dependent insulinotropic polypeptide (GIP) are important regulators of insulin secretion, and their functional loss is an early characteristic of type 2 diabetes mellitus (T2DM)." (PMID 25191754, 2014). "DPP-4is stabilize postprandial levels of bioactive GLP-1 and GIP and have been approved for the treatment of type 2 diabetes." (PMID 23696840, 2013). "Though there is no conclusive evidence in the literature suggesting an altered expression of GIP, it has been shown that, in type 2 diabetes, the overall incretin effect is reduced and this was mainly attributed to altered functioning of GIP." (PMID 20673334, 2010). "While, GIP secretion is normal in type 2 diabetics, these individuals are relatively resistant to the acute insulinotropic effect of exogenous GIP administration." (PMID 20376212, 2009). "While its insulinotropic action is reportedly attenuated or abolished with worsening of glycaemic control in type 2 diabetes (T2D), the relationship between GIP and glucagon secretion across different levels of glycaemic control remains unclear." (PMID 41943672, 2026). "The study aims to characterize the secretion dynamics of glucagon-related peptides, including GLP-1, GIP, and GLP-2, across different stages of metabolic-associated steatotic liver disease (MASLD), while evaluating the impact of type 2 diabetes (T2D) on these hormonal responses." (PMID 41649634, 2026). "The SURPASS trials showed Tirzepatide, a dual GIP/GLP-1 receptor agonist, led to clinically significant weight loss in individuals with type 2 diabetes with an average weight reduction of 7–14% of body weight and a substantial proportion of participants achieving weight reductions of 15% or more." (PMID 40565841, 2025).
type 2 diabetes (continued). "Tirzepatide, a novel dual GIP and GLP-1 receptor agonist, has shown promising efficacy in modulating biomarkers associated with non-alcoholic steatohepatitis (NASH) among individuals with type 2 diabetes." (PMID 41001122, 2025). "In a diabetes type 2 context, endogenous GIP stimulation alone has been shown insufficient to lower blood glucose while in another study, both gastric emptying and the secretion of GLP‐1 were identified as the most relevant determinants of postprandial glycemia." (PMID 39619994, 2024). "However, the reduced incretin effect of GIP is recovered in those with type 2 diabetes once hyperglycemia has improved, indicating that the reduced incretin effect of GIP is reversible." (PMID 40607157, 2024). "One study however showed that targeting GIP alone was insufficient to lower glucose in a diabetes type 2 context, while another study identified GLP‐1 secretion and gastric emptying, among numerous other glucoregulatory factors, as the most relevant determinants of postprandial glycemia." (PMID 39619994, 2024). "Because of its insulin-secreting property, GIP could be a potential therapeutic strategy for the treatment of type 2 diabetes patients." (PMID 39273671, 2024). "Mounjaro, a dual GLP-1 agonist and GIP (glucose-dependent insulinotropic polypeptide), received approval for use in the management of type 2 diabetes mellitus in May 2022." (PMID 39553073, 2024). "Both GIP and GLP1 are susceptible to degradation by the enzyme dipeptidyl peptidase 4 (DPP-4), which has prompted the development of DPP-4 inhibitors as a treatment for type 2 diabetes mellitus." (PMID 38398492, 2024). "In addition, a supra-additive effect of SU in combination with high concentrations of intravenous gastric inhibitory polypeptide (GIP) has also been shown in HNF1A maturity-onset diabetes of the young and in T2DM treated with standard dose glipizide." (PMID 38267622, 2024). "When compared to type 2 diabetes mellitus patients without periodontitis, gastric inhibitory polypeptide (GIP) and GLP-1 were shown to be elevated, and GIP was associated with a diagnosis of periodontitis, which is defined as a pocket depth greater than 4 mm." (PMID 38337597, 2024). "However, patients with type 2 diabetes often exhibit resistance to GIP, resulting in diminished GIP-mediated insulinotropic effects." (PMID 39610482, 2024). "The use of this GIP/GLP-1 dual agonist in individuals with type 2 diabetes has shown superiority with respect to HbA1c lowering, body-weight reduction, improvement in lipid profile and reduction of arterial blood pressure, as compared with placebo, semaglutide or insulin." (PMID 37542009, 2023). "Therefore, it was not until the mid-1980s that the results of administering exogenous (porcine) GIP to individuals with type 2 diabetes were reported." (PMID 37430117, 2023). "Due to the short half-life (< 2 min) of the degradation of GLP-1 and GIP by DPP-IV, the inhibition of DPP-IV is an attractive therapeutic strategy to maintain the insulinotropic activity of GLP-1 and GIP, resulting in an improved homeostasis of glucose in type II diabetes." (PMID 37284652, 2023). "GIP is one of the incretin hormones, located in the β-cells, adipose tissue & in brain where it plays an important role in the type-2 diabetes mellitus and other metabolic disorders by boosting the insulin response which is triggered by the post-prandial rise in glycemia." (PMID 36782201, 2023). "Tirzepatide (a new dual GLP-1/GIP agonist) displayed better and clinically relevant hemoglobin A1c (HbA1c) reduction when compared to insulin glargine in persons with type 2 diabetes (T2D) and increased cardiovascular risk, with a reduced incidence of hypoglycemia." (PMID 37859909, 2023). "GLP-1/GIP peptide (Tirzepatide) has also been FDA-approved for treating type-2 diabetes." (PMID 38017205, 2023).